POTEB3 (POTE ankyrin domain family member B3)
Synonyms: POTE-15
Tractability: PROTAC: ubiquitination databases record sites on it.
Gene: Protein-coding gene on chromosome 15 (21,405,401 to 21,440,499, reverse strand). Ensembl gene ENSG00000278522.
Gene Ontology:
Molecular function: protein binding
Genetic constraint (gnomAD): Loss-of-function variants: 0 observed, 9.98 expected, observed/expected ratio (o/e) 0, 90% interval 0 to 0.3. That is too few expected variants to judge how well the gene tolerates losing a copy. Missense variants: 10 observed, 151.66 expected, observed/expected ratio (o/e) 0.0659, 90% interval 0.04 to 0.11. Synonymous variants: 3 observed, 45.56 expected, observed/expected ratio (o/e) 0.0659, 90% interval 0.029 to 0.17.
Homologues: Paralogues in human: POTED (96% identical), POTEB (93% identical), POTEB2 (93% identical), POTEC (90% identical), POTEI (87% identical), POTEF (87% identical), POTEE (87% identical), POTEJ (82% identical), POTEH (78% identical), POTEG (77% identical), POTEM (77% identical), POTEA (58% identical), and 2 more.
Diseases named in the same sentence as POTEB3 in open-access papers:
POTEB3 is named in the same sentence as 1 disease in open-access papers, as found by Europe PMC text mining. Sharing a sentence is not in itself a finding about the gene and the disease. The quoted sentences say what the papers report.
cancer (1 paper, 2025). A tumor composed of atypical neoplastic, often pleomorphic cells that invade other tissues. "In binary analyses, replication revealed POTEB3 rs2605913 (p = 2.8 × 10-8), while meta-analysis (n = 13,652) uncovered SLC25A37 rs952825245 (p = 5.15 × 10-12), a locus associated with cancer and vitamin D signaling." (PMID 41096749, 2025).